NXF3 (nuclear RNA export factor 3)
Description:
May function as a tissue-specific nuclear mRNA export factor.
Tractability: No criterion of Open Targets' tractability assessment is met for any kind of drug.
Gene: Protein-coding gene on chromosome X (103,075,810 to 103,093,143, reverse strand). Ensembl gene ENSG00000147206.
Subcellular location: Nucleus; Cytoplasm
Subcellular location (Human Protein Atlas): Nucleoplasm
Gene Ontology:
Molecular function: protein binding; RNA binding; nucleic acid binding
Biological process: mRNA export from nucleus; poly(A)+ mRNA export from nucleus
Cellular component: cytoplasm; nuclear RNA export factor complex; nucleoplasm; nucleus
Homologues: Orthologues: chimpanzee NXF3 (92% identical), macaque NXF3 (89% identical), dog NXF3 (61% identical), mouse Nxf3 (50% identical), rat Nxf3 (49% identical), tropical clawed frog nxf1 (40% identical), zebrafish nxf1b (38% identical), zebrafish nxf1a (34% identical), Caenorhabditis elegans nxf-1 (20% identical), Caenorhabditis elegans nxf-2 (17% identical), Drosophila melanogaster nxf4 (9% identical). Paralogues in human: NXF2 (54% identical), NXF2B (54% identical), NXF1 (51% identical).
Diseases named in the same sentence as NXF3 in open-access papers:
NXF3 is named in the same sentence as 9 diseases in open-access papers, as found by Europe PMC text mining. Sharing a sentence is not in itself a finding about the gene and the disease. The quoted sentences say what the papers report.
cervical cancer (1 paper, 2014). A primary or metastatic malignant neoplasm involving the cervix. "Although Crm1 is overexpressed in various types of human cancer, including glioma, cervical cancer and renal cell carcinoma, and has the potential to be a prognostic marker for cancer, the clinical relevance of NXF3 in human cancer remains undetermined." (PMID 24520286, 2014).
Infertility (1 paper, 2025). "Hence, it remains to be clarified whether the infertility in the NXF3 LoF subject is a consequence of impaired mRNA export at later stages of spermatogenesis or a consequence of other NXF3-related functions." (PMID 40624043, 2025).
oligoasthenoteratozoospermia (1 paper, 2025). A form of male infertility that is characterized by a combination of low number or oligozoospermia, poor motility or asthenozoospermia, and abnormal shape or teratozoospermia of sperms. "In summary, the man with the NXF3 LoF variant had quantitatively and qualitatively severely impaired sperm production (oligoasthenoteratozoospermia)." (PMID 40624043, 2025).
cancer (2 papers, 2014 to 2019). A tumor composed of atypical neoplastic, often pleomorphic cells that invade other tissues. "In conclusion, the findings provide evidence that implicates NXF3 as a prospective predictor of HCC prognosis as well as a potential therapeutic target for cancer treatment." (PMID 24520286, 2014). "In summary, NXF3, as an NXF family member, has for the first time, to the best of our knowledge, been demonstrated to be linked to human cancer, extending its role into tumor development." (PMID 24520286, 2014). "NXF3 has been identified as a nucleocytoplasmic shuttle protein and demonstrated to induce RNA export by recruitment of Crm1, which is overexpressed in various types of human cancer." (PMID 24520286, 2014). "Therefore, such factors (including Crm1 and NXF3) that are involved in RNA or protein export may yield novel therapeutic targets for cancer treatment." (PMID 24520286, 2014). "Furthermore, NXF3 was identified to be correlated with the overall and recurrence-free survival time in postoperative patients with HCC, suggesting that NXF3 may be a promising prognostic marker for HCC as well as a novel RNA export pathway for targeting with cancer therapies." (PMID 24520286, 2014).
tumor (1 paper, 2014). "NXF3 staining was mainly observed in the nucleus of the tumor cells." (PMID 24520286, 2014). "Furthermore, the clinically relevant data presented showed that patients with HCC and high tumor NXF3 expression levels had decreased OS times and earlier TTR compared with those of patients with low tumor NXF3 expression levels." (PMID 24520286, 2014). "The overexpression of NXF3 in the HCC tissues was correlated with decreased survival time [hazard ratio (HR) = 1.954, 95% confidence interval (CI) = 1.034–3.695, P=0.039] and earlier tumor recurrence (HR = 2.101, 95% CI = 1.186–3.722, P=0.011) in postoperative patients with HCC." (PMID 24520286, 2014). "A study has shown that NXF3 may mediate the downregulation of the levels of transforming growth factor β3 (TGF-β3) mRNA expression and protein secretion in Sertoli cells, and TGF-β3 is considered to be involved in tumor progression." (PMID 24520286, 2014).
NXF3 also shares sentences with these, for which no sentence is quoted: glioma (1 paper); hepatocellular carcinoma (1); male infertility (1); renal cell carcinoma (1).